TRIQK (triple QxxK/R motif containing)
Description:
May play a role in cell growth and maintenance of cell morphology.
Synonyms: C8orf83; DKFZp779L1068; PRO0845; LOC286144; UPF0599
Tractability: Antibody: UniProt predicts a signal peptide or a membrane-spanning region.
Gene: Protein-coding gene on chromosome 8 (92,883,530 to 93,017,786, reverse strand). Ensembl gene ENSG00000205133.
Subcellular location: Endoplasmic reticulum membrane
Gene Ontology:
Cellular component: endoplasmic reticulum membrane
Genetic constraint (gnomAD): Loss-of-function variants: 0 observed, 0.61 expected, observed/expected ratio (o/e) 0, 90% interval 0 to 1.82. That is too few expected variants to judge how well the gene tolerates losing a copy. Missense variants: 18 observed, 19.74 expected, observed/expected ratio (o/e) 0.91, 90% interval 0.63 to 1.35. Synonymous variants: 9 observed, 9.32 expected, observed/expected ratio (o/e) 0.97, 90% interval 0.58 to 1.64.
Homologues: Orthologues: chimpanzee TRIQK (100% identical), dog TRIQK (95% identical), pig TRIQK (92% identical), rabbit TRIQK (91% identical), guinea pig TRIQK (90% identical), rat Triqk (90% identical), mouse Triqk (88% identical), zebrafish triqk (66% identical).
Diseases named in the same sentence as TRIQK in open-access papers:
TRIQK is named in the same sentence as 1 disease in open-access papers, as found by Europe PMC text mining. Sharing a sentence is not in itself a finding about the gene and the disease.
TRIQK shares sentences with these, for which no sentence is quoted: influenza (1 paper).